CAV1 (caveolin 1)
Diseases named in the same sentence as CAV1 in open-access papers (continued):
Sharing a sentence is not in itself a finding about the gene and the disease.
tumor (continued). "Besides, the results of tumor microenvironment analysis suggested that ANXA5, STAT1, CD44, CAV1, and ANXA2 expression was positively correlated with the infiltration of B cell, CD8+ T cell, CD4+ T cell, macrophages, neutrophils, and dendritic cells." (PMID 40607003, 2025). "The role of Cav-1 in fibroblast phenotypes is controversial: Cav-1 depletion in NIH-3T3 fibroblasts promotes cell growth, while its expression enhances the release of inflammatory and tumor-promoting factors, supporting tumor cell proliferation and migration." (PMID 40230452, 2025). "A study of the role of CAV1 in 60 patients with extrahepatic cholangiocarcinoma showed that CAV1 was expressed only in tumor cells, but not in normal paracancer tissues." (PMID 40304434, 2025). "Furthermore, the co-localization of CaO2 NPs with Caveolin-1 and SPARC was observed in tumor sections." (PMID 40429837, 2025). "Furthermore, tumor samples treated with BA exhibited an increase in Cav-1 expression and a notable decrease in c-Myc and PDK1 levels in tumor tissues, providing evidence that a dosage of 250 mg/kg BA can effectively suppress glycolytic activity in vivo." (PMID 38563878, 2024). "Likewise, the protein levels of three well-established SCLC tumor markers—NSE, CAV1, and MYCL1—were elevated in drug-resistant cells." (PMID 39594767, 2024). "Four weeks later, the size and weight of the tumour in the CAV-1 knockdown group was considerably decreased compared with that in the control U87 group, the size and weight of the tumour in the CAV-1 over-expression group was considerably increased compared with that in the control U251 group." (PMID 38298655, 2024). "Taken together, this substantial evidence strongly confirms that these HMDRGs (ZFP36, SERPINE1, AKAP12, CAV1, and DUSP1) are strongly involved in hypoxia, mitochondrial dysfunction, and tumor immunity, in turn contributing to the modulation of GC pathogenesis and prognosis." (PMID 39165353, 2024). "This study revealed the role of Cav-1 in BC metastasis, particularly in lung metastasis, without affecting primary tumor growth." (PMID 39244591, 2024). "The derived CAV1 tertile classifications are relative to a population and not based on absolute cut-offs for each tumor." (PMID 38509243, 2024). "We do not know the mechanism by which statins induce Akt1/Cav1 downregulation; nevertheless, statin-mediated attenuation of the Akt and mTOR signaling pathways has already been correlated with reduction of tumor burden in different cancers." (PMID 38473215, 2024). "However, as a bioenergetic drug, its effects on metabolic coupling markers (Cav1, MCT4) and the factors involved in tumor-fibroblast interactions (IL-6, TGFβ, and acid lactic) are not thoroughly and simultaneously examined." (PMID 38361760, 2024). "At the end of week 4, clear metastatic tumor lesions were visible in the lungs of the WT control group but not in the Cav-1 KO group." (PMID 39244591, 2024). "The level of exosomal caveolin-1 in plasma was significantly higher in PCa patients with high PSA levels, clinical-stage T3 or T4 and in the group of PCa patients with aggressive PCa compared to favorable clinicopathological features or tumor aggressiveness." (PMID 38542507, 2024). "Among these genes, PKM, CAV1, GLI3, PICK1, PRPF6, and UBE3A have been identified as oncogenes, and play a pivotal role in orchestrating tumor-host interactions, fostering tumor growth, promoting metastasis, enhancing resistance to therapy, and ensuring cellular survival." (PMID 38280969, 2024). "Unlike what is seen in cancer cells, where caveolin-1 exhibits varying effects across different transformed tissues, its expression in the stromal cells in tumor microenvironment seems to follow a more consistent pattern in relation to tumor progression." (PMID 38067108, 2023). "The effect of CAV1 genotypes appeared to be independent of tumor characteristics including CAV1 protein expression." (PMID 37017811, 2023).
tumor (continued). "Thus, the ability of PGE2 to promote tumor growth was essentially limited to those conditions where B16F10 cells expressed both E-cad and CAV1." (PMID 38069269, 2023). "Cav1 interacts with CD36 and affects lipid synthesis, thereby affecting tumor metastasis." (PMID 37910338, 2023). "Moreover, we also checked the protein–protein interaction (PPI) network of CAV1 and found it is highly connected with Caveolin-2 and EGFR, which are important factors for tumor progression." (PMID 37642765, 2023). "In prostate cancer, the secretion of Cav-1 by tumor cells leads to an increase in the non-adhesion growth ability of tumor cells." (PMID 37056561, 2023). "Notably, TIPARP was highly expressed in the tumor relative to the normal group expression, and CD24, TACC1, HSD17B10, and CAV1 were less expressed in the tumor relative to the normal group." (PMID 37907864, 2023). "Through paracrine and/or autocrine, exosomes derived from tumor cells or stromal cells deliver growth factors, extracellular enzymes, or other factors necessary for tumor growth to promote tumor progression, such as transforming growth factor-β1 (TGF-β1), Caveolin-1, and Wnt." (PMID 35692747, 2022). "IHC staining of tumor tissues from mice treated with B3GALT4 knockdown 9464D cells confirmed the expression levels of CXCL9 and CXCL10, and the percentage of CD8A-positive cells was increased after MβCD treatment, while caveolin-1 was decreased." (PMID 36284313, 2022). "However, the addition of mevalonate, an intermediate metabolite of cholesterol formation, restricted the tumor cell suppression and reinduced the CAV-1 expression in ATV-treated cells, demonstrating the tight link between cholesterol and CAV-1." (PMID 35203491, 2022). "CAV-1-depleted fibroblasts exhibit increased levels of intracellular cholesterol and improved TGF-β1 levels via AKT activation, contributing to the metastatic behavior of tumor cells." (PMID 36115986, 2022). "Similarly, in vivo analysis has demonstrated that ATV-treated resistant xenograft models had decreased cholesterol levels inducing downregulation of the CAV-1/GLUT-3 axis, abrogating the glucose uptake, and resulting in lower tumor volumes." (PMID 35203491, 2022). "Immunoexpression of caveolin-1 in the cytoplasm and membranes of the epithelial tumor cells of the AM samples was negative in 22 (26.5%) samples and positive in 61 (73.5%) samples." (PMID 33037799, 2021). "Perhaps not surprisingly we found a significantly greater tumour expression of Cav-1 in patients with a poor performance status (<60 Karnofsky scale, P<0.0005)." (PMID 34490102, 2021). "Cav1 expression (subgroups, H-score or mRNA) was not correlated with tumor differentiation, age, sex, tumor stage (T1 to T4) or lymph node status (p > 0.05)." (PMID 34207120, 2021). "In addition, PS binding contributes to the interaction of DLC1-START with Caveolin-1 and PLCD1, and to the tumor suppressor functions of DLC1 that are RhoGAP-independent." (PMID 34727930, 2021). "The individual functions of the two isoforms of Cav-1 are not fully elucidated in the context of tumor progression, yet." (PMID 33774714, 2021). "High tumour expression of Cav-1 had a negative effect upon survival in both the Proneural (P=0.041) and Mesenchymal (P=0.035) subtypes." (PMID 34490102, 2021). "The epithelial (tumor) portion of the PDAC samples showed an increase in the expression of ATP13A3 (polyamine import) and SLC3A2 (diamine exporter) and lower expression of CAV1." (PMID 34945011, 2021). "No statistical difference was observed in respect to the tumour expression of Cav-1 and survival in either the Classical or Neural subtypes (respectively)." (PMID 34490102, 2021). "Until now, all studies only have considered the total Cav-1 expression in tumors and no other studies exist in the literature on the expression profile of the two isoforms of Cav-1 in tumor cells." (PMID 33774714, 2021).
tumor (continued). "Although CD34 staining indicated that angiogenesis occurring in all tumors, smaller and thinner blood vessels were found in caveolin-1 siRNA-expressing SMMC7721 tumor sections compared to negative control tumors in the spleen." (PMID 32676485, 2020). "A retrospective patient cohort study revealed that nearly 90% of estrogen receptor (ER) positive DCIS patients that had recurred to IBC showed diminished or completely absent Cav-1 expression in their tumor stroma." (PMID 32633727, 2020). "The literature indicates that FASN promotes the proliferation, invasion and migration of tumor cells by interacting with various molecules, including nonstructural protein 5B and caveolin-1." (PMID 32699531, 2020). "However, N-myc downstream-regulated gene 1 (NDRG1), a tumor suppressor, inhibits the pathogenesis of CRC through CAV-1 degradation-mediated inhibition of EMT." (PMID 32456226, 2020). "Our results show that Macrocybin differentially affects the actin cytoskeleton of tumor vs. nontumor cells and that this mechanism is mediated by changes in the expression of Caveolin-1." (PMID 33353176, 2020). "Altogether, these findings indicate that CAV1 function as a tumor suppressor in the absence of E-cadherin, involves NOS inhibition, which reduces HIF1α S-nitrosylation and VEGF expression." (PMID 32825247, 2020). "The role of CAV1 in EMT appears to be cell/tissue specific, or stage/specific in tumours, since in other experimental systems CAV1 may in fact promote cellular EMT and invasion." (PMID 32811813, 2020). "These previous findings regarding the function of caveolin-1 in cancer led us to hypothesize that caveolin-1 could induce VEGF expression in HCC cells, subsequently enhancing tumor angiogenesis and promoting HCC invasiveness." (PMID 32676485, 2020). "The migration of immune cells to tumor environment is the first step to exert their effects, therefore we selected the genes related to leukocyte migration, including IL-1β, ITGA4, ITGB2, ITGB7, CAV1, and MAG." (PMID 32358484, 2020). "Intriguingly, however, L-NAME administration to mice injected with B16F10(Mock) cells did not reduce tumor size beyond the effect attributable to CAV1 presence in B16F10(CAV1) cells." (PMID 32825247, 2020). "To elucidate how CAV1 functions as a tumor suppressor in the absence of E-cadherin, we first evaluated E-cadherin protein levels in a panel of four different cancer cell lines." (PMID 32825247, 2020). "Caveolin-1 negative, glycolytic fibroblasts dramatically promote tumor growth with a ∼4-fold increase in tumor mass and ∼8-fold increase in tumor volume." (PMID 32532126, 2020). "SWIR imaging at 24-h and 36-h time points indicated differential localization of nanoprobes based on their distinct SWIR emissions, with increased accumulation of CAV1 targeted nanoprobes in the 4175TR tumor, and increased accumulation of CXCR4 targeted nanoprobes in the MCF7 tumor." (PMID 33172421, 2020). "The tumor stroma showed signs of a reactive response with increased type 2 (CD163+) macrophage infiltration, vascular density and hyaluronic acid, and reduced levels of caveolin-1, androgen receptors, and mast cells." (PMID 30980038, 2019). "LNCaPCAV1 cells injected into one flank of nude mice promoted tumor growth of LNCaP cells (initially lacking CAV1) injected into the contralateral flank of the animal." (PMID 31362353, 2019). "Re-expression of Cav-1 in MTLn3 can inhibit the EGF-induced lamellipod biogenesis and cell migration, prevent the anchorage-independent growth, and suppress the invasion and metastasis of tumor cells." (PMID 31759347, 2019). "In non-SQC, tumor cells maintained a low level of Cav-1 expression in BM compared with the primary lesion (27% vs. 30%, respectively, P = 0.564)." (PMID 31297035, 2019).
tumor (continued). "Taken together, LINC81507 is decreased in NSCLC and functions as a sponge to miR-199b-5p to regulate CAV1/STAT3 pathway, which suggests that LINC81507 serve as a tumor suppressor and potential therapeutic target and biomarker for metastasis and prognosis in NSCLC." (PMID 31296840, 2019). "Similarly, genes such as CAV1, ACACB, NTRK2, KLF4, and MYH11 were the key down-regulated hub genes suggesting a possible role of their decreased expression in breast carcinogenesis." (PMID 31292488, 2019). "Our findings demonstrate that Cav1 mediates glucose uptake via GLUT3 in TKI-resistant but not in TKI-sensitive tumor cells." (PMID 31534543, 2019). "The slight increase in expression of CAV-1 in CC NM I T compared to CC NM I N shows a different response to that determined by proteomics analysis where a decrease in tumor was observed as compared to the non-cancer tissue (UDD)." (PMID 31889941, 2019). "Cav1 reconstitution in Cav1-depleted NSCLC cells demonstrates that Cav1 exerts its oncogenic effect through the regulation of glucose uptake via GLUT3, which is important to maintain the energy demand for tumor growth." (PMID 31534543, 2019). "Although the median OS was shorter in patients with high Cav-1 expression than in those with low Cav-1 expression in tumor cells, the difference was not statistically significant (71.0 vs. 73.1 months, respectively, P = 0.260)." (PMID 31297035, 2019). "Collectively, tumor cells in the primary lung lesion showed higher Cav-1 expression in the SQC group than in the non-SQC group." (PMID 31297035, 2019). "The Cav1 MDA-MB-435 pseudopod proteome included galectin-3 supporting a role for local pCav1-galectin-3 signaling to drive invadopod protrusion and tumor cell invasion." (PMID 31803361, 2019). "In general, the loss of stromal Cav-1 through autophagy is a negative prognostic factor during tumor progression, while the autophagy of tumor cells modulated by Cav-1 has different function in cancer progression." (PMID 31759347, 2019). "It has been proposed that the absence of stromal Cav-1 via autophagy is a negative prognostic factor during tumor progression." (PMID 31759347, 2019). "Caveolin-1 has been shown to beessential for stiffness sensing, and thus when silenced, tumor cells are able toproliferate and migrate independent of the rigidity of the surrounding ECM." (PMID 31069311, 2018). "In addition to tumor promoting effect on cancer cells, FASN and Cav-1 have been reported to protect cancer cells from chemotherapy by inducing drug resistance." (PMID 29568521, 2018). "Even though, the efficacy of nab-paclitaxel predicted by stromal Cav-1 levels seems not to be influenced by the tumor-promoting functions of Cav-1 in stromal tissue." (PMID 30348118, 2018). "We found that MIM-B and caveolin-1 were differentially expressed between tumor tissues and normal tissues." (PMID 29221140, 2017). "Western blotting revealed that FASN protein expression was elevated in CRC tissues, while real-time PCR and Western blotting indicated that FABP1, CD36 and Caveolin-1 mRNA and protein levels were reduced in CRC, potentially due to the reduced availability of exogenous lipids for the tumor." (PMID 28938608, 2017). "We found that Cav-1 reciprocally regulates MEK and ERK in low- and high-expressing tumor cells." (PMID 29141593, 2017). "As it is not possible to target Cav1 specifically in tumor cells it is important to dissect the molecular details of Cav1-mediateded radiation response modulation." (PMID 28112237, 2017). "As cordycepin upregulated CAV1 expression and JNK phosphorylation, and inhibited phosphorylation of Foxo3a in vitro, we next examined CAV1, the phosphorylation status of JNK, total JNK, p-Foxo3a, and total Foxo3a protein in tumor tissues by immunohistochemistry." (PMID 28099944, 2017). "Using clodronate depletion of macrophages, we demonstrate that macrophage Cav1 signaling is critical for metastasis and not for primary tumor growth." (PMID 29212030, 2017).
tumor (continued). "Although primary tumor growth and weight were not different between both groups of chimeric mice, Cav1 KO→WT chimeras had 2-fold more lung metastases than WT→WT chimeras." (PMID 29212030, 2017). "In line with previous reports we found that benign prostate epithelia were negative for Cav1 but that Cav1 expression in prostate epithelial cells increased with higher Gleason scores, i.e. lower tumor differentiation (bold arrows)." (PMID 28112237, 2017). "Cav-1 expression is known to be regulated mainly by inactivation of oncogenes or inactivation of tumor suppressive genes, TGF-β, and oxidative stress in the tumor microenvironment." (PMID 28828003, 2017). "Together, these data suggest that Cav1 in BMDCs has an anti-metastatic function in the lungs without affecting primary tumor growth at other sites." (PMID 29212030, 2017). "Tumoural tissue presented higher expression levels of CAV1 compared with surrounding non-tumoural tissue." (PMID 29022911, 2017). "Re-expression of Cav1 in these settings restored Akt phosphorylation and rescued the defect of tumor cell invasion after ClpP, but not ClpX knockdown." (PMID 27389535, 2016). "Taken together, the data obtained here suggest that Dsg2 may play a significant role in tumor development by positively regulating EGFR level and signaling through a c-Src and Cav1 dependent manner." (PMID 26918609, 2016). "In ES CAV1 seems to regulate indirectly MMP-9 transcription, thus promoting tumor metastasis." (PMID 27487136, 2016). "Both tumor growth and anchorage-independent cell survival are negatively impacted by Cav1 overexpression." (PMID 26918609, 2016). "In tumour tissues from the BGC-823-xenografted nude mice treated with DT-13-TPT combination, the positive areas for TUNEL, cleaved caspase-3 and NM IIA were increased, while the positive areas for p-ERK1/2, EGFR and Cav-1 were reduced." (PMID 27105508, 2016). "We were the first to show that expression of CAV1 in human TSCC in the TME components was higher than in the tumor cells and that it had a negative impact on the clinical outcomes." (PMID 25633184, 2015). "Hence, caveolin-1, IQGAP1, or cholesterol-rich membrane microdomains (lipid rafts) are potential therapeutic targets for prevention or treatment of tumor metastasis." (PMID 25924234, 2015). "Downregulation of Cav1 induced EMT and enhanced tumor cell invasion in various cancer cell lines." (PMID 26474461, 2015). "Similarly, mRNA and protein levels of CAV1 and β-catenin (total and pSer675 protein) were also increased in NRAS-ΔPTEN tumours compared with NRAS." (PMID 26307673, 2015). "Additionally, it was recently discovered that BHB is upregulated in caveolin-1 null mice and proposed that epithelial cancer cells directly take in stromal-derived BHB to drive tumor progression and eventual metastasis." (PMID 25879199, 2015). "In line with the previous reports, we found that benign prostate epithelia were negative for Cav1 but that Cav1 expression in prostate epithelial cells increased with higher Gleason scores, that is, lower tumor differentiation (bold arrows)." (PMID 25985209, 2015). "The contribution of CAV1 to cancer progression, whether expressed in the cancer cells or in the TME components, seems to be complex and controversial and apparently tumor-related as well." (PMID 25633184, 2015). "This replication study will only address the effects of Cav1 expression in tumor stroma and remodeling of the tumor microenvironment matrix, and will not replicate the effects of p190RhoGAP in this model." (PMID 26179155, 2015). "In addition, a series of tumor suppressors including deleted in liver cancer 1 (DLC-1), INK4a and RB, were revealed to be closely correlated to Cav-1 status." (PMID 26431273, 2015). "In accordance, preliminary study showed that cells expressing low levels of Cav1 exerted strong resistance to anoïkis (not shown), a prerequisite for systemic circulation and secondary tumor formation in distant organs." (PMID 26474461, 2015).